CTLA4 (cytotoxic T-lymphocyte associated protein 4)
Diseases named in the same sentence as CTLA4 in open-access papers (continued):
Sharing a sentence is not in itself a finding about the gene and the disease.
cancer (continued). "Immune checkpoint therapies, including mAbs that target CTLA-4, PD-1, or PD-L1, can enhance antitumor immune responses and have led to several recent and significant clinical advances in cancer treatment." (PMID 29212254, 2017). "The CTLA-4 blocking antibody ipilimumab has entered clinical trials for the treatment of different human cancers." (PMID 28938692, 2017). "Further subgroup analyses were conducted and categorized by experimental methods, CTLA-4 sources and cancer types." (PMID 28211499, 2017). "Immune checkpoint inhibitors (ICPI), such as ipilimumab [anti-cytotoxic T-lymphocyte antigen-4 (CTLA-4) antibody] and nivolumab or pembrolizumab [anti-programmed cell death protein-1 (PD-1) antibodies], improve survival in several cancer types." (PMID 28204866, 2017). "Immune checkpoint inhibitors, targeting the molecules CTLA-4, PD-1 and PD-L1, showed efficacy against several type of cancers and are currently used in clinical practice." (PMID 29245905, 2017). "Immune checkpoints, however also diminish desired T cell responses and blocking coinhibitory receptors like PD-1 or CTLA-4 was shown to be effective in cancer treatments." (PMID 29029399, 2017). "The recent success of immunotherapies targeting the immune checkpoint molecules, CTLA-4, PD-1, and PD-L1 for the treatment of cancer has emphasized the essential role of the immune system for eradicating tumors." (PMID 28515944, 2017). "Recent clinical success of the anti-PD-1 and anti-CTLA-4 immune checkpoint inhibitors has offered an optimistic future for cancer patients." (PMID 28894087, 2017). "Fueled by recent clinical success, cancer immunotherapy using antibodies that specifically target CTLA-4 and the PD-1/PD-L1 axis to block immune inhibitory pathways is emerging as a promising future for cancer therapy." (PMID 29197379, 2017). "In T cell-inflamed tumors, immune failure appears to occur at the effector phase, and some patients with this type of tumor show good clinical responses to cancer vaccines, high-dose interleukin (IL)-2, anti-CTLA-4, and anti-PD-1 antibodies." (PMID 28695111, 2017). "Our analysis also observed increased expression of sur- and in-CTLA-4 expressing lymphocytes in cancer patients." (PMID 28211499, 2017). "Immune-checkpoint blockades (i.e., blocking PD-1, PD-L1, or CTLA-4) have shown durable clinical effects on some patients with various advanced cancers." (PMID 29112124, 2017). "Selective enhancements of T cell activation using PD-1 or CTLA-4 blocking antibodies have been demonstrated to be a suitable strategy for cancer immunotherapy." (PMID 29190910, 2017). "Immune checkpoint inhibitors have achieved remarkable progress in tumor treatment, and two vital checkpoint receptors, CTLA-4 and the programmed death-1 receptor (PD-1), have been studied most extensively in clinical cancer immunotherapy." (PMID 28938692, 2017). "Aside from cancer, PD-1 and CTLA-4 expression was elevated in other immune mediated diseases such as acute hepatitis A infection, hepatitis C infection, and HIV infection." (PMID 30873473, 2017). "Taken together, our study suggests inhibition of ENTPD2 as a promising strategy to increase the efficacy of PD-1/CTLA-4 immune checkpoint inhibitor in cancer treatment." (PMID 28894087, 2017). "James Allison, director of the UC Berkeley Cancer Research Laboratory, was intrigued with a molecule called cytotoxic T-lymphocyte antigen-4 (CTLA-4), originally discovered in a cDNA library derived from activated T-cells." (PMID 28050779, 2017). "Of the many immune checkpoint receptors under intensive investigation, the three best characterized ones in the context of clinical cancer immunotherapy are PD-1, CTLA-4 and IDO, which function by different mechanisms, as detailed below." (PMID 27756892, 2017). "Ipilimumab (Bristol–Myers Squibb) targets CTLA-4, blocking the inhibitory signal, unleashing cytotoxic T cells to eliminate the cancer cells." (PMID 28970830, 2017).
cancer (continued). "Ten healthy adults and 45 cancer patients were analyzed for gene expression of PD-1, CTLA-4, CD25, CD28, IL-10, TGF-β and Foxp3 in peripheral blood." (PMID 28881603, 2017). "Expression of PD-1 and CTLA-4 in cancer patients was significantly increased compared to that in healthy adults(p=0.04)." (PMID 28881603, 2017). "Immune-checkpoint blockade (i.e., blocking PD-1, PD-L1, or CTLA-4) has shown durable clinical effects in some patients with various advanced cancers." (PMID 29112124, 2017). "PD-1 inhibition alone is active in about 30% of cancer patients, but in combination with CTLA-4 the fraction of responding metastatic melanoma patients increases to 57%." (PMID 28421069, 2017). "Immune checkpoints or coinhibitory receptors, such as cytotoxic T lymphocyte antigen (CTLA)-4 and programmed death (PD)-1, play important roles in regulating T cell responses, and they were proven to be effective targets in treating cancer." (PMID 28545567, 2017). "Targeting T-cells regulatory proteins, such as CTLA-4 and PD-1 by checkpoint blocking antibodies has been strengthened the area of cancer immunotherapy." (PMID 28878676, 2017). "These trials include agents such as cancer vaccines, CTLA-4 inhibitors, PD-1 inhibitors, and PD-L1 inhibitors." (PMID 28929083, 2017). "Monoclonal antibodies targeting CTLA-4 (e.g., ipilimumab, tremelimumab) have emerged as potent weapons against cancer and show great promise in treating a broad range of diverse tumor types." (PMID 29225597, 2017). "Blockade of the immune checkpoints CTLA-4 and PD-1/PD-L1 has recently emerged as a promising strategy in the development of effective cancer immune therapies." (PMID 28611299, 2017). "Anti-CTLA-4 and anti PD-1 act in different point of cancer- immune cycle (in priming phase and killing cancer cells phase respectively): while anti CTLA4 enhances early T cell activation, anti-PD-1 reverse the exhausted state of existing effector T cells." (PMID 29245905, 2017). "Patients with several different cancer types have shown encouraging responses in clinical trials investigating the efficacy of checkpoint-inhibitors targeting CTLA-4 and/or PD-1." (PMID 28947968, 2017). "Recent advancement has indicated that the expression of immune-inhibitory checkpoints such as PD-1/PD-L1 and CTLA-4 function as potent mediators for the balance and escape phases of cancer immune editing." (PMID 28878676, 2017). "As CTLA-4 and PD-1 axis inhibition becomes adopted for more cancer types, rare irAE presentations are becoming more common." (PMID 28716137, 2017). "In support of this notion, combination of E7046 and anti-CTLA-4 antibodies, known to reduce Treg cells in both cancer patients and preclinical models, was superior to either agent alone." (PMID 28920002, 2017). "The goal of current cancer immunotherapy, using anti-PD-L1:PD-1 and anti-CTLA-4 antibodies, is to initiate or reinitiate a self-sustaining cycle of cancer immunity, enabling it to amplify and propagate without creating an unrestrained response." (PMID 29075294, 2017). "Immune checkpoint factors, such as programmed cell death protein-1/2 (PD-1, PD-2) or cytotoxic T lymphocyte-associated antigen-4 (CTLA-4) receptors, are targets for monoclonal antibodies (MAbs) developed for cancer immunotherapy." (PMID 28572863, 2017). "Recent reports indicate that immune checkpoint blockade antibodies (e.g. anti‐CTLA‐4 and anti‐PD‐1) enhance T cell antitumour activity and have produced exciting and durable results in treatment of a number of cancers." (PMID 28401653, 2017). "Recent clinical successes of immune checkpoint inhibitors highlight the potential of novel immune modulating agents in cancer immunotherapy, either as stand-alone therapeutics or in combination with anti-PD-1 and anti-CTLA-4 therapy." (PMID 28497796, 2017). "And the results also show that CTLA4 is a membrane protein and plays the role of immune checkpoint in cancer development." (PMID 31725860, 2017).
cancer (continued). "Grade 3–4 AE rates of up to 12% due to PD-1/PDL1 blockade and up to 18% due to CTLA-4 blockade have been reported in cancer patients." (PMID 29237435, 2017). "Despite these advancements, significant gaps exist in cancer immunotherapy, as only a subset of cancers have demonstrated clinical response to CTLA-4 and PD-1 targeted therapies." (PMID 29211042, 2017). "Immunotherapeutic strategies have shown significant promise for treatment of cancers resistant to conventional modalities, leading to Food and Drug Administration approval of agents targeting the CTLA-4 and PD-1 pathways." (PMID 28194010, 2017). "In conclusion, the meta-analysis indicated that no significance was found when analyzing the overall effect of CTLA-4 expression on OS in several of cancer cases." (PMID 28211499, 2017). "It has been established and shown that CTLA-4 protein expression appears to be important for tumors to evade host immune surveillance in cancers." (PMID 28211499, 2017). "Fortunately, the modern era would revive the importance of the immune system in battling cancer by releasing the brakes or checkpoints (anti-CTLA-4 and anti-PD-1/PD-L1) that have been holding the immune system at bay." (PMID 28050779, 2017). "We also verify another two immune checkpoints PD-L1 and CTLA4 have positively correlation with CD163 in cancer cells." (PMID 29152078, 2017). "Cancer immunotherapy was proposed decades ago but has only recently been realized as a promising approach to cancer treatment due to the success of immunomodulating anti-CTLA-4 and anti-PD-1 monoclonal antibodies against various of cancers." (PMID 28469973, 2017). "The immunomodulatory role of gut microbiota on cancer therapeutics is also apparent with immune checkpoint blockade therapies, such as blockade of CTLA-4 by ipilimumab." (PMID 28716068, 2017). "There is also a significant correlation between CTLA-4 expression and overall survival in different cancer cases." (PMID 29225597, 2017). "A number of clinical trials are investigating the side effects, dosage, and efficacy of PD-1 and CTLA-4 monoclonal antibodies for treating patients with HIV- and hepatitis-associated cancers [reviewed in Ref." (PMID 29033936, 2017). "ICTs have proven effective in treating a number of difficult to treat types of cancer by blocking PD-L1/PD-1 and CTLA-4 checkpoint pathways." (PMID 28430133, 2017). "The CTLA-4 +49AA genotype was identified in this study to be an independent adverse prognostic indicator in cancer patients." (PMID 28211499, 2017). "Immune checkpoint inhibitors targeting cytotoxic T lymphocyte antigen 4 (CTLA-4) and programmed death receptor 1 (PD-1) have been proven highly effective in fighting cancer." (PMID 28300768, 2017). "Our search retrieved 331 articles after initial searching for pooled estimates of HR, which is utilized to explore the correlations between CTLA-4 expression and clinical data of cancer patients." (PMID 28211499, 2017). "Nevertheless, CTLA-4 +49AA genotype was an independent adverse indicator for cancer prognosis, while the high-expression of sCTLA-4 has a tendency to be correlated with the prolonged OS." (PMID 28211499, 2017). "Currently, CTLA-4 and PD-1 inhibitors have been approved for cancer immunotherapy in clinics while TIM-3 and LAG-3 inhibitors are being tested in clinical trials." (PMID 27835902, 2016). "The intracellular trafficking pathways that control the transport of CTLA-4 to the cell surface influence the degree of inhibition and the potency of antibody checkpoint blockade in cancer immunotherapy." (PMID 26918337, 2016). "During cancer, T cells express a high level of CTLA-4, so that, cancer can evade the cytotoxic effect of T cells." (PMID 27686848, 2016). "The monoclonal antibodies ipilimumab (anti-CTLA-4) and nivolumab (anti-PD-1) have shown remarkable antitumor activity in an increasing number of cancers." (PMID 27610613, 2016).
cancer (continued). "A recent study has shown promising indications for utilizing the ICOS-ICOS-L pathway in the context of anti-CTLA-4 immunotherapy for cancer treatment." (PMID 27235509, 2016). "Numerous studies have shown that immune checkpoint inhibitors such as CTLA-4 or PD-1 blockade are effective in different types of cancers; yet, the response rates remain at 20–30%." (PMID 27835902, 2016). "The oncolytic activity of the vector was demonstrated in CTLA-4-positive ovarian, prostate and lung cancer cells, as well as human cancer xenografts in nude mice." (PMID 28536390, 2016). "Ipilimumab (Yervoy), a humanized monoclonal antibody specific for cytotoxic T lymphocyte-associated antigen-4 (CTLA-4), was the first FDA-approved drug from this new class of cancer immunotherapies." (PMID 26961085, 2016). "The rationale for using anti-CTLA-4 in cancer therapy was to unleash pre-existing anticancer T cell responses and possibly trigger new ones." (PMID 27151159, 2016). "Immunotherapies with checkpoint blockade antibodies that block CTLA-4 and PD-1 (or its ligand PD-L1) can restore and augment cytotoxic T-cell responses against cancers, leading to durable responses and prolonged overall survival with tolerable toxicity." (PMID 27776338, 2016). "In an inflamed tumour microenvironment, engagement of PD-1 or CTLA-4 can self-limit the antitumor immune responses and permit cancer cells to proliferate unrestrained." (PMID 27796306, 2016). "These antibodies have generated remarkable responses in a wide spectrum of cancers and have shown better clinical benefit and better toxicity profile than CTLA4-blocking antibodies." (PMID 28018338, 2016). "The hope is that these new cancer vaccines, alone or in combination with CTLA-4 and PD-1 checkpoint blockade, will increase the duration and quality of life of patients with cancer." (PMID 27660710, 2016). "Inhibitory ligands, such as PD-L1, PD-L2 and CTLA-4, on cancer cells inhibit T cell proliferation and activation." (PMID 27854240, 2016). "CTLA4 is also expressed by several cancers/tumors and this mechanism corresponds with immune tolerance as seen in cancer progression." (PMID 28116316, 2016). "Such strategy has met high clinical success, especially with specific antibodies directed against inhibitory molecules on T cells such as PD1 and CTLA-4 in cancer patients." (PMID 27405665, 2016). "Immune checkpoint blockade of the inhibitory immune receptors PD-L1, PD-1 and CTLA-4 has emerged as a successful treatment strategy for several advanced cancers." (PMID 27147225, 2016). "In recent years significant progress has been made in developing of specific monoclonal antibodies to inhibit CTLA-4 as a potent strategy in cancer immunotherapy." (PMID 27686848, 2016). "Although CTLA-4 expression by T cells during acute antigen exposure is transient, chronic antigen exposure, as in cancer, leads to sustained expression of CTLA-4." (PMID 27050369, 2016). "In the studies reported here, while levels of total Tregs were similar to healthy donors, cancer patients had increased levels of CTLA-4+ Tregs, which is a phenotype of a biologically suppressive Treg." (PMID 28936253, 2016). "The clinical successes of anti-PD-1 and anti-CTLA-4 suggest that overcoming T cell exhaustion represents a promising therapeutic approach to treat cancers." (PMID 28123897, 2016). "Combination therapy with α-CTLA-4 and α-PD-1 has shown significant clinical responses in different types of cancer." (PMID 27498556, 2016). "Monoclonal antibodies (mAbs) that modulate inhibitor signaling by CTLA-4 and PD-1, e.g., ipilimumab, pembrolizumab, and nivolumab, are now in wide clinical use for several cancers." (PMID 28018344, 2016). "Our study provides evidence that CTLA-4 promotes cancer progression, perhaps through impairment of host T cell-mediated immunity as has recently been reported." (PMID 27050369, 2016).
cancer (continued). "Four years after the approval of the first checkpoint inhibitor ipilimumab (anti-CTLA-4) for advanced melanoma in 2011, cancer immunotherapy is now considered one of the pillars of cancer therapy." (PMID 26981243, 2016). "Cancer immunotherapy, by blocking inhibitory receptors such as CTLA-4 and PD-1/PD-L1, is being actively studied and applied to the treatment of various cancers, including melanoma, and lung and kidney cancers." (PMID 27741514, 2016). "Intriguingly, MFIs of BTLA or CTLA-4 on CD4+ T cells from cancer patients were significantly higher than that from normal donors." (PMID 27577071, 2016). "Monoclonal antibodies which block the CTLA-4 or PD-1 receptors have been recently approved by the FDA for treatment of certain forms of human cancers." (PMID 27186886, 2016). "Studies reporting cases of cancer develop irAEs following treatment with anti CTLA-4 (ipilimumab) or anti PD-1 (nivolumab or pembrolizumab) antibodies were included." (PMID 27472273, 2016). "Nevertheless, a synergistic effect of trametinib plus anti-PD-1, anti-PD-L1, or anti-CTLA-4 was observed in the preclinical CT26 carcinoma model." (PMID 27847783, 2016). "Several attempts have been made to develop cancer vaccines specific binding tumor-associated antigens, including MAGEs, CD20, CTLA-4, and MUC1, with the goal of inducing antigen-specific CTLs for cancer therapy." (PMID 26417929, 2015). "Given the “up-to-date” subject and the emergence of cancer immunotherapy, increasing reports of anti-CTLA-4-induced irAEs are published." (PMID 26337719, 2015). "With the recent clinical success in applying CTLA-4 and PD-1 blockade to the treatment of a variety of tumors, the promise of cancer immunotherapy has begun to be realized." (PMID 25941561, 2015). "Recently, remarkable advances have been recognized in the cancer immunotherapy field, such as clinical success in anti-CTLA-4 antibody or anti-PD1 antibody, and the upcoming T cell therapy including chimeric antigen receptor-T cells." (PMID 26625258, 2015). "Inhibition of immune checkpoints implicated in immune cells exhaustion inside the tumors such as cytotoxic T-lymphocyte antigen 4 (CTLA-4) or PD-1/PD-L1 pathway has led to durable clinical responses in many cancers and in some cases to long-term remission." (PMID 31557983, 2015). "Immune checkpoint blockade with antibodies to CTLA-4 and PD-1 represents a promising cancer therapy that aims to restore an efficient antitumoral response mediated by T cell." (PMID 26303618, 2015). "Currently, antibodies blocking checkpoint proteins such as anti-cytotoxic T-lymphocyte antigen-4 (CTLA-4) and anti-programmed cell death-1 (PD-1) have been approved to treat cancer and shown to impart durable clinical responses." (PMID 26580645, 2015). "BRAF inhibitors and anti-CTLA-4 and anti-PD-1 monoclonal antibodies are changing the landscape of cancer treatments." (PMID 25660021, 2015). "Two receptors, cytotoxic T-lymphocyte-associated antigen 4 (CTLA4) and programmed cell death protein 1 (PD-1), have been actively studied in cancer for their potential roles as inhibitory receptors." (PMID 26470780, 2015). "As a negative regulator of T-cell immunity, CTLA-4 is an attractive target for cancer immunotherapy." (PMID 25893809, 2015). "The clinical value of anti-CTLA-4 antibodies is being investigated in various cancer types including prostate, renal, bladder, colorectal, esophageal, pancreatic, gastric, hepatocellular, and pulmonary malignancies as well as mesothelioma and lymphoma." (PMID 26337719, 2015). "Even more recently, the discovery of cytotoxic T lymphocyte antigen-4 (CTLA-4) and programmed death-1 receptor (PD-1) as potential targets has opened the door on immuno-oncological therapies for cancer management." (PMID 26371045, 2015).